CRP (C-reactive protein)
Diseases named in the same sentence as CRP in open-access papers (continued):
Sharing a sentence is not in itself a finding about the gene and the disease.
Sepsis (continued). "In our previous study of 102 critically ill severe sepsis and/or trauma patients with MODS, we aimed to assess the prognostic value and daily trend of IL-6, nCD64 expression, CRP and lipopolysaccharide-binding protein (LBP) in relation to the outcome measure of hospital mortality." (PMID 34945111, 2021). "In addition, this study confirmed that the accuracy of clinical sepsis diagnosis based on PSP values was similar to that of diagnoses based on PCT and CRP values." (PMID 33879189, 2021). "These parameters, especially CRP, may also play an important role in predicting SIRS or sepsis, and could be examined in the future regarding predictive quality." (PMID 34068849, 2021). "Recent and earlier definitions of sepsis do not include well established pro-inflammatory biomarkers, such as CRP or PCT, although clinicians—and particularly burn specialists—commonly use them to support their decision-making process to diagnose sepsis." (PMID 34442346, 2021). "CRP and lactate levels were higher in the sepsis group than in the non-sepsis group; however, the differences in the percentages were not as large as those for the IG%." (PMID 34915849, 2021). "In this study, several inflammatory biomarkers, including HBP, CRP, IL-6, N%, PCT, and D-dimer, could significantly predict sepsis." (PMID 34778149, 2021). "In summary, our study showed that lactate, CRP, and procalcitonin were independent predictors of short-term survival and ICU admission in cancer patients presenting to the ED with suspected infection/sepsis." (PMID 34439240, 2021). "The difference in the CRP was apparent between the patients suffering sepsis and those who did not within hours after admission." (PMID 34884171, 2021). "The negative predictive value of serial CRP was 100% in deciding the duration of antibiotics therapy in suspected neonatal septicemia up to 7 days." (PMID 34899922, 2021). "CRP was predictive of sepsis at 1 and 3 days postop; however, it was no longer predictive of sepsis at day 3 when applied to the complicated patients only." (PMID 34065206, 2021). "Additionally, our goal was to assess how well pro-inflammatory biomarkers (WBC, CRP, PCT, PSP) reflect the event of sepsis depending on its type of definition." (PMID 34442346, 2021). "Nevertheless, when removing sepsis-related CRP values from the analysis, there was no statistical difference among groups." (PMID 34834472, 2021). "Other biomarkers such as CRP and TLC could also play a role both independently and in conjunction with AEC to predict outcomes and mortality in cirrhotic patients with sepsis and SIRS." (PMID 33585129, 2021). "Neither the CRP level nor the WBC count was significantly different between the sepsis and severe sepsis groups (P > 0.05)." (PMID 34778149, 2021). "Additionally, CRP and PCT are the most common required biomarkers for sepsis diagnosis, prognosis, and therapeutic decision-making." (PMID 34679578, 2021). "MDW, which can be measured along with CBC, has a diagnostic performance comparable to those of conventional biomarkers, such as CRP and PCT; hence, it could be an early marker of sepsis and help decide further evaluation of sepsis." (PMID 33857210, 2021). "However, the ability of HBP to predict progression to sepsis in children with severe CAP was inferior to PCT, D-dimer, CRP, IL-6, and N%." (PMID 34778149, 2021). "Furthermore, the best values of NLR, CRP, PCT, and MR-proADM for a diagnosis of sepsis were lower than the values reported from previous studies (10, 5 mg/dL, 0.5 ng/mL, and 1.5 nmol/L respectively)." (PMID 34441017, 2021). "PCT, procalcitonin; CRP, C-reactive protein; LOS, late-onset sepsis." (PMID 34522543, 2021). "Similarly, sepsis biomarker ordering as a standard of care was different by sites (PCT and CRP in LPS, CRP only in UHG)." (PMID 34193208, 2021).
Sepsis (continued). "In addition to CRP and PCT, the concentrations of the circulating anti-inflammatory cytokines IL-Ra and IL-10 were found to be significant in discriminating between sepsis and SIRS55–57." (PMID 34675320, 2021). "CRP and PCT are currently the most frequently used biomarkers of sepsis in clinical practice." (PMID 33810263, 2021). "It has been documented that CRP is correlated with acute physiology and chronic health evaluation II (APCHE II) and sequential organ failure assessment (SOFA) score, which reflect the severity and prognosis of sepsis." (PMID 34447386, 2021). "Although CRP levels are usually elevated even in patients without signs of sepsis and who are on immunosuppressive drugs, suppression of CRP in patients treated with TCZ can delay the diagnosis of serious infections." (PMID 34533616, 2021). "The areas under the receiver operating characteristic curves (AUROCs) for sepsis discrimination with WRS, procalcitonin (PCT), CRP, and IL-6 are 0.864, 0.727, 0.625, and 0.651, respectively, indicating that WRS has better predictive value than other clinical factors of sepsis." (PMID 33926067, 2021). "It's worth noting that we found that the increase in the abundance of family Enterococcaceae bacteria, including family Enterococcaceae, genus Enterococcus, and Enterococcus durans in gut of patients with sepsis is positively correlated with the increase in blood indicators WBC and CRP." (PMID 33898360, 2021). "Univariate analysis of PCT, PCT/Alb, CRP, and CRP/Alb between survival and non-survival groups in patients with sepsis-induced AKI." (PMID 34141715, 2021). "The purpose of our study was to assess the correlation among inflammation markers Serum C reactive protein (CRP), procalcitonin (PCT), and nutritional marker albumin (Alb) and 90-day mortality in sepsis-induced AKI and to put more attention on the combined markers (CRP/Alb and PCT/Alb)." (PMID 34141715, 2021). "Compared to PSEP, CRP levels were higher at T2 in neonates with shock (median 8.2 mg/dL, IQR 4.2–14.9) and sepsis (median 5.9 mg/dL, 2.2–11.3) compared to those with infection (median 2.6 mg/dL, 1.4–5.5), while PCT was higher at T2 and T4 only in neonates with shock compared to those with infection." (PMID 34068959, 2021). "Biomarkers are used to diagnose and monitor patients with sepsis, but C-reactive protein (CRP) is proven not predictive at onset of late onset neonatal sepsis (LONS) diagnosis." (PMID 33407770, 2021). "Interestingly, when CRP stimulation was combined with PRR ligand stimulation, as for example, occurs in the context of sepsis, IL-23 production by monocytes was strongly reduced." (PMID 34769069, 2021). "LASSO regression analysis identified C-reactive protein (CRP) and HLA-DRA mRNA as being repeatedly associated with sepsis, and no model was found to perform better than CRP alone in this setting (ROC-AUC 0.76 (0.68–0.84))." (PMID 34945111, 2021). "Compared with APAP-treated PD-1–/– mice, APAP-treated WT mice had a higher fold change of C-reactive protein (CRP) and lactate levels and a cytokine profile that favored a proinflammatory imbalance, as indicated by increased sepsis severity markers such as IL-6 and a higher IL-6/IL-10 ratio." (PMID 33320839, 2021). "In addition to these proinflammatory cytokines, upregulation of the levels of C-reactive protein (CRP) and procalcitonin (PCT) are other biomarkers of sepsis." (PMID 34499695, 2021). "An updated systematic review found that interleukin (IL)-6, IL-8, C-reactive protein (CRP) and procalcitonin (PCT) were predictive of bacteraemia and severe sepsis as compared to a range of other biomarkers however the optimal thresholds in FN remain unknown." (PMID 34093531, 2021). "Thus, biomarkers of inflammation or infection, such as procalcitonin (PCT), C-reactive protein (CRP), interleukin-6 (IL-6), neopterin, and pro-adrenomedullin (pro-ADM), have a significant role in the diagnosis and management of sepsis." (PMID 33810263, 2021).
Sepsis (continued). "In our opinion, measurement of CRP and PON1 could be an advisable tool to support a clinical diagnosis of sepsis and predict the outcome in routine practice." (PMID 34072427, 2021). "Nine differentially expressed proteins that might be related to sepsis and SIRS were tested further by ELISA, and CRP, LRG1, and SAA were chosen as the target biomarkers." (PMID 34675320, 2021). "A single-centered, observational study conducted the elevated CRP, neutrophil lymphocyte ratio (NLR), and lactate dehydrogenase in non-survivors, and non-survivors were more likely to develop acute respiratory distress syndrome, CRS, and sepsis." (PMID 34447386, 2021). "PCT is a polypeptide indicated in sepsis for the identification of non-systemic inflammatory response syndrome and CRP is a terminal biomarker for differentiating between inflammatory response and sepsis." (PMID 34654440, 2021). "However, few studies have compared MDW with C-reactive protein (CRP) and procalcitonin (PCT), well-known biomarkers of sepsis." (PMID 33857210, 2021). "Neutrophil L-selectin (AUC 0.692 [95%CI 0.574–0.810]) and monocyte L-selectin (AUC 0.761 [95%CI 0.632–0.891]) were significant predictors of sepsis and were not significantly different to CRP (AUC 0.772 [95%CI 0.650–0.853])." (PMID 34065206, 2021). "The aim of this study was to evaluate the diagnostic accuracy and prognostic value of NLR, PLR, and MLR in patients with sepsis and septic shock outside the intensive care unit (ICU) and to compare them with C-reactive protein (CRP), PCT, MR-proADM, SIRS, qSOFA, and SOFA scores." (PMID 34441017, 2021). "Pearson correlation coefficient analysis revealed that the levels of CRP and PCT, as well as APACHE II score and SOFA score were positively correlated with miR-29c-3p in sepsis patients (P < 0.001), indicating that the level of miR-29c-3p is positively correlated with the severity of sepsis." (PMID 34376255, 2021). "Areas under receiver operating characteristic curves (AUROCCs) on the day of sepsis diagnosis according to the blinded EAC were similar for all three biomarkers {PSP, 0.75 [95% confidence interval (CI) 0.67–0.82]; CRP, 0.77 [95% CI 0.69–0.84] PCT, 0.75 [95% CI 0.68–0.83]}." (PMID 33879189, 2021). "Five hundred and fifty-three patients (36.5%) fell in the subgroup of the low pretest probability of sepsis (no CRP or PCT ordered by the emergency physicians)." (PMID 34193208, 2021). "The age of the data is also a weakness, since data on sepsis markers as procalcitonin and CRP were either absent or scarce in the oldest of the datasets, TREAT04." (PMID 34425790, 2021). "In this prospective, observational study, we investigated the diagnostic value and optimal cut-off points of serum PCT and CRP levels for sepsis and infection without sepsis in elderly critically ill patients." (PMID 34344141, 2021). "This study aimed to evaluate whether presepsin could be a useful marker for detecting sepsis or severe sepsis, and whether it could predict therapeutic courses in patients with UTI compared with other markers, such as PCT or CRP." (PMID 34641833, 2021). "The intervention selected was discontinuation of antibiotics within 5 days for neonates with gestational age ≥ 37 weeks, no documented signs or symptoms of sepsis, CRP ≤ 10 mg/L and negative cultures within 3 days of antibiotic initiation." (PMID 33803250, 2021). "Herein, we found that the values of PCT, PCT/Alb, CRP, and CRP/Alb were significantly higher in the non-survival group and that PCT, PCT/Alb were independent risk factors for poor prognosis in patients with sepsis-induced AKI." (PMID 34141715, 2021). "Procalcitonin (PCT) shows better prediction of sepsis compared to CRP; nevertheless, there is a reported lack of accuracy." (PMID 34301187, 2021). "In this study, the AUC for CRP and NLR was statistically significant for the diagnosis of sepsis." (PMID 33643735, 2021).
Sepsis (continued). "Markers currently in use, such as CRP, PCT, and interleukin 6 (IL-6), were repeatedly found to be compared with each other in the literature review to justify its superiority in diagnosis of sepsis." (PMID 33803628, 2021). "Although acute phase reactants, such as leukocyte count, CRP, and PCT, are considered in the diagnosis of sepsis and bacterial infections in elderly patients, their reliability and the optimal cut-off points in the diagnosis of IWS and S have not been sufficiently determined." (PMID 34344141, 2021). "Therefore, present study was conducted to compare performance of procalcitonin, CRP, TLC and lactate compared to blood culture in critically ill patients admitted with suspicion of sepsis." (PMID 34912433, 2021). "Broad spectrum antibiotic therapy covering gram positive, negative, and anaerobes is common practice until sepsis has been excluded, with negative blood cultures and normal infection markers of white cell count and C-reactive protein (CRP)." (PMID 32500050, 2020). "From this data it appears that an acute inflammatory event, in this case sepsis, induces a longer-term glycosylation remodeling on AACT, even though that the abundance levels of AACT (and CRP) return to baseline levels and the patients have been released from the ICU." (PMID 33519818, 2020). "In contrast to our results and the previous veterinary studies, in human patients with severe sepsis, CRP was significantly higher in non-surviving patients – surprisingly even without an overlap of the patient groups on the day of admission." (PMID 32434519, 2020). "The recommended durations of antibiotic therapy for sepsis has little evidence rationale; indeed, CRP- and PCT- guided reduction in antibiotic therapy duration is currently being investigated in the ADAPT-Sepsis trial and is due to complete in April 2021." (PMID 33114715, 2020). "However, CRP, PCT, and other inflammatory indicators are also significantly increased in sepsis patients and have been proposed as potential markers for diagnosing neonatal sepsis." (PMID 32792679, 2020). "Compared with hs-CRP and SAA, PCT had a higher clinical application value for sepsis, and PCT could be used as a reliable index for the early diagnosis of sepsis." (PMID 33235597, 2020). "In correspondence to inflammatory biomarkers such as C-reactive protein (CRP) or erythrocyte sedimentation rate (ESR), the levels of alarmins correlate with disease activity in several inflammatory conditions, such as sepsis, rheumatoid arthritis, Kawasaki disease, or idiopathic bowel disease." (PMID 32377165, 2020). "In addition, the results of our study also suggested that PCT had the best logistic regression coefficient and area under the ROC curve (AUC), indicating that PCT had higher clinical application value than hs-CRP and SAA in the early diagnosis of sepsis." (PMID 33235597, 2020). "If there are any signs of sepsis or white cell count is too high, CRP is high, patient is not clinically well, we start the patient on antibiotics anyway." (PMID 33869463, 2020). "Therefore, CRP has been used as a prognostic factor in patients with heart failure, ICH, ischemic stroke, and sepsis." (PMID 32344777, 2020). "Of the 228 neonates with suspected sepsis, 94 (41.2%) had a positive CRP, while 134 (58.8%) had a negative CRP." (PMID 32238170, 2020). "Interestingly they also suggested that using a PCT/CRP ratio has a potential role in differentiating blood-culture proven sepsis from cases of suspected sepsis; this outperformed both PCT and CRP for this particular purpose." (PMID 32164268, 2020). "Recent study indicated that on the 2nd, 3rd, and 5th days, serum CRP level was higher in the nonsurvivor group than in the survivor group, and serum CRP has good clinical prognostic value for patients with sepsis and septic shock." (PMID 32410872, 2020). "However, most common biomarkers for sepsis diagnosis including PCT, CRP, and interleukin 6 have limited specificity and sensitivity." (PMID 32214905, 2020).
Sepsis (continued). "The ROC curves showed that SIRT1 predicted 28-day mortality risk in sepsis patients, and its predictive value was not inferior to Scr, albumin, WBC, and CRP, while less than SOFA score and APACHE II score." (PMID 33263643, 2020). "However, the sepsis group had higher levels of Scr, WBC, CRP, and PCT in the serum, while had lower serum albumin levels than healthy group (all P < 0.001), and the differences reached significant level." (PMID 32188465, 2020). "Although PCT is considered superior to CRP in many studies, it is not a definitive test for diagnosing sepsis because PCT levels can also be increased in other conditions." (PMID 32503670, 2020). "Lactic acid and CRP are the most widely used markers to determine the severity of sepsis and its progression, but they are not specific markers of sepsis." (PMID 32153412, 2020). "The mean age (P = .006), percentage of patients smoking (P = .021), the percentage of patients with COPD (P = .004), CRP (P = .001), APACHE II score (P < .001), and SOFA score (P = .038) were increased in ARDS‐sepsis patients compared with non‐ARDS‐sepsis patients." (PMID 31967348, 2020). "A high proportion of infants treated for culture-negative sepsis exhibited a mild elevation of CRP (<5 mg/dl) [baseline phase = 9/10 infants (90%), QI-study phase: 16/24 infants (66%) and surveillance phase: 4/7 infants (57%)]." (PMID 32766501, 2020). "In the sepsis group, uNGAL levels were not significantly correlated with serum CRP levels on ICU day 1 (rs = 0.114), day 2 (rs = 0.077), and day 3 (rs = 0.262)." (PMID 31988752, 2020). "Similarly, even presumed sepsis cases were identified expeditiously during the hospital stay based on the abnormal CBC and/or elevated CRP levels." (PMID 32766501, 2020). "On the basis of the obtained results, the authors concluded that, taken alone, sTREM-1 is not better than PCT or CRP as a marker for the diagnosis of sepsis in the forensic setting." (PMID 33092081, 2020). "Given that high fever and elevated CRP level indicated potential sepsis, an antibiotic was used until the confirmation of negative blood cultures." (PMID 32282733, 2020). "Nevertheless, most studies have failed to establish an objective correlation between CRP level and severity of the sepsis." (PMID 33266250, 2020). "A study of 300 septic and non-septic patients showed that the combination of age and gender with CRP and PCT levels could yield a positive diagnosis of sepsis." (PMID 32636717, 2020). "Analyzing the results of sepsis markers revealed that the median procalcitonin (PCT) level of all the studied neonates was 10.4 ng/ml and the range was (0.1–50.6) ng/ml, median CRP serum level was 48 mg/dl and ranged 4–140 mg/dl and IL-6 ranged from 5–120.8 pg/ml with median serum level 36.1 pg/ml." (PMID 33061986, 2020). "However, in our study, we compared the levels of NLR with procalcitonin, CRP, and SOFA score as a marker of sepsis." (PMID 33178505, 2020). "Comparison of sTREM-1 to PCT and CRP for diagnosis of sepsis has been performed, with results suggesting that sTREM-1 may have better performance (AUCs 0.82, 0.77 and 0.72 for sTREM-1, PCT and CRP, respectively)." (PMID 32164268, 2020). "As for the biochemical markers, the most investigated in literature for a sepsis diagnosis were PCT and CRP: the first one is an acute phase mediator whose increase is observed in all conditions characterized by an inflammatory response, while PCT is a more specific marker for bacterial sepsis." (PMID 33092081, 2020). "From this, a negative CRP can be useful for deciding discontinuation of antibiotic therapy if the clinical features of sepsis are absent." (PMID 32238170, 2020). "Endocan levels, compared to PCT and CRP levels, were measured in blood and pericardial fluid samples obtained post mortem from 16 sepsis cases and 16 non-sepsis control cases." (PMID 33092081, 2020).